MCL1 (MCL1 apoptosis regulator, BCL2 family member)
Diseases named in the same sentence as MCL1 in open-access papers (continued):
Sharing a sentence is not in itself a finding about the gene and the disease.
ovarian carcinoma (continued). "In this study, we find that in certain lung and ovarian cancer cell lines, USP9X knockdown does not alter MCL1 protein levels." (PMID 29335437, 2018). "However, ABT-737 does not target Mcl-1 and inhibiting Mcl-1 and/or inducing its BH3-only partners (Bim, Puma and Noxa) represent a rational strategy to sensitize ovarian carcinoma cells to ABT-737 10,11." (PMID 32424251, 2020).
prostate carcinoma (100 papers, 2001 to 2025). A carcinoma that arises from epithelial cells of the prostate gland. "The anti-apoptotic proteins, specifically BCL2, BCL2L1 (Bcl-xL), and MCL1, are often overexpressed in cancer and are associated with resistance and disease progression in prostate cancer." (PMID 40704654, 2025). "Here, we evaluated the change of Mcl-1 protein levels in human tissue samples during prostate cancer progression as well as the underlying mechanism responsible for the change of Mcl-1 protein levels in two prostate cancer cell lines." (PMID 37173959, 2023). "Sensitivity to apoptosis induced by BAD dephosphorylation and loss of MCL-1 expression varies among prostate cancer cell lines as does the expression of anti- and pro-apoptotic BCL proteins." (PMID 30871232, 2019). "Overexpression of MCL-1 has been associated with advanced prostate cancer, including high Gleason grade primary tumors and metastatic tumors, and hematopoietic malignancies." (PMID 24040284, 2013). "In contrast, treatments that induce simultaneous BAD dephosphorylation and MCL-1 loss trigger rapid apoptosis in prostate cancer cells." (PMID 24040284, 2013). "Following the single-agent assessment of sensitivity to Mcl-1 inhibition in prostate cancer cells, S63845 was evaluated in combination with other BH3 mimetics to determine synergistic effects on cell viability." (PMID 40704654, 2025). "Using transcriptomic data from patients with mCRPC in the SU2C/Prostate Cancer Foundation cohort, we observed that Mcl-1 and Bcl-xL had higher expression than Bcl-2, indicating that Mcl-1 and Bcl-xL are potential targets in mCRPC." (PMID 40704654, 2025). "Previous studies have demonstrated that androgen deprivation suppresses androgen receptor (AR) signaling, resulting in decreased or dysregulated MCL1 expression and increased apoptosis in prostate cancer cells." (PMID 40872527, 2025). "β-elemonic acid inhibits growth of human castration-resistant prostate cancer cells through the suppression of JAK2/STAT3/MCL-1 signal pathways." (PMID 40830747, 2025). "We initially assessed responses to navitoclax (targeting BCL-2/BCL-XL), venetoclax (targeting BCL-2), and S63845 (targeting MCL-1) in a series of prostate cancer PDX-derived primary cultures/3D spheroids, patient-derived organoids, and cell lines." (PMID 40436896, 2025). "Several anti-apoptotic members of the bcl-2 gene family, including BCL2, BCL-X, and MCL-1 showed high expression during the progression of prostate cancers." (PMID 38195593, 2024). "In summary, our experiments revealed that deubiquitinase USP9x is able to regulate sensitivity to radiotherapy by increasing Mcl-1 levels, thereby elevating the threshold for apoptosis induction in prostate cancer cells." (PMID 37173959, 2023). "Of these examined tissue probes, 45 prostate cancer samples and 10 benign prostate tissue samples were used to correlate Mcl-1 and USP9x levels." (PMID 37173959, 2023). "Downregulation of Mcl-1 or USP9x levels improved the response of prostate cancer cells to radiotherapy." (PMID 37173959, 2023). "We detected increased protein levels of deubiquitinase USP9x, an enzyme known to increase Mcl-1 protein stability, during prostate cancer progression, which was positively correlated with Mcl-1 levels." (PMID 37173959, 2023). "Our findings suggest that deubiquitinase USP9x is responsible for upregulated Mcl-1 protein levels, thereby contributing to prostate cancer progression and therapy resistance." (PMID 37173959, 2023). "We demonstrated a concurrent upregulation of Mcl-1 and USP9x protein levels during prostate cancer progression." (PMID 37173959, 2023).
prostate carcinoma (continued). "We, therefore, compared gene expression of MCL1 in normal prostate samples (n = 52) and prostate cancer samples (n = 492) using data sets at the GEPIA platform." (PMID 37173959, 2023). "Since high Mcl-1 protein levels often coincided with high USP9x protein levels at higher stages during prostate cancer progression, a posttranslational stabilization by USP9x provides here a credible explanation for elevated Mcl-1 levels." (PMID 37173959, 2023). "Single-cell transcriptomics in prostate cancer revealed the high expression of MCL1 in persistent senescent tumor cells, a kind of metabolically active cell that promoted tumor proliferation and metastatic dissemination." (PMID 36937870, 2023). "Here, we evaluated protein levels of Mcl-1 and USP9x, a deubiquitinase regulating Mcl-1 protein stability, in human tissue samples during prostate cancer progression." (PMID 37173959, 2023). "So far, our results demonstrated that USP9x controls Mcl-1 protein levels and, in this way, regulates the response to radiotherapy in prostate cancer cells." (PMID 37173959, 2023). "Several published papers have found that NF-κB binds to the promoters of BCL2, BCL2A1, and MCL1 and activates their expression in many cell types, such as prostate cancer cells, esophageal squamous carcinoma cells, and fibrosarcoma cells." (PMID 36853387, 2023). "Our immunohistological analysis suggests that translational or posttranslational regulation of Mcl-1 protein levels becomes more important during prostate cancer progression." (PMID 37173959, 2023). "We, therefore, analyzed the protein levels of several Bcl-2 family members, including Mcl-1, in both prostate cancer cell lines." (PMID 37173959, 2023). "Here, we analyzed the role of anti-apoptotic Mcl-1 and USP9x, a deubiquitinase stabilizing Mcl-1 protein levels, in prostate cancer progression and response to radiotherapy." (PMID 37173959, 2023). "We demonstrate that protein levels of deubiquitinase USP9x and anti-apoptotic Mcl-1 increased during prostate cancer progression." (PMID 37173959, 2023). "We confirmed this stabilizing effect of USP9x on Mcl-1, particularly in LNCaP prostate cancer cells." (PMID 37173959, 2023). "No change in Bcl-2, Bcl-xL, or Bax/Bak expression was observed in prostate cancer PC-3 cells in one study, while other authors have detected Mcl-1 degradation in liver cancer cells." (PMID 36675536, 2023). "MCL1 gene was expressed at similar levels in normal prostate and prostate cancer tissue (left box plot)." (PMID 37173959, 2023). "In prostate cancer cells, however, ionizing radiation resulted in decreased Mcl-1 protein levels in PC3 cells but increased Mcl-1 levels in LNCaP cells." (PMID 37173959, 2023). "We provided evidence that regulation of Mcl-1 stability is a factor determining the response of prostate cancer cells to radiotherapy." (PMID 37173959, 2023). "Levels of anti-apoptotic proteins Bcl-2, Bcl-xL, and Mcl-1 are upregulated in prostate cancer and contribute to prostate cancer progression." (PMID 37173959, 2023). "Especially at advanced prostate cancer stages, increasing numbers of specimens displayed increased USP9x immunoreactivity together with increased Mcl-1 immunoreactivity." (PMID 37173959, 2023). "Anti-apoptotic Mcl-1 was found to be targeted by miRNA-3614-5p, which reveals that prostate cancer cells with lower miRNA-3614-5p expression have higher malignant properties." (PMID 35457012, 2022). "Our findings highlight the crucial role of miRNA-3614-5p in regulating Mcl-1 anti-apoptotic signaling in human prostate cancer cells." (PMID 35457012, 2022). "Suppression of Mcl-1 expression by norcantharidin is shown to induce mitochondrial-dependent apoptosis in human prostate cancer cells, which suggests that Mcl-1 plays an important role in regulating the progression of human prostate cancer." (PMID 35457012, 2022). "We further explored the mechanism behind miRNA-3614-5p-reduced Mcl-1 in human prostate cancer cells." (PMID 35457012, 2022).
prostate carcinoma (continued). "EA is also known to suppress the growth of prostate cancer cells and trigger the apoptosis of castration-resistant prostate cancer cells by attenuating the JAK2/STAT3/MCL-1 and NF-κB signaling pathways." (PMID 35242040, 2022). "Recently, scRNA sequencing of prostate cancer cells from Ptenpc−/− and Ptenpc−/−;Timp1−/− mouse models showed Mcl‐1 induction upon senescence." (PMID 36065138, 2022). "We show that the efficacy of Docetaxel treatment, a standard of therapy for metastatic castration-resistant prostate cancer patients, can be enhanced by the concomitant administration of Mcl-1 inhibitors both in vitro and in vivo." (PMID 35449130, 2022). "To clarify the role of Mcl-1 in prostate cancer cells, we utilized the knockdown assay for Mcl-1 in human PC3 and 22Rv1 cells." (PMID 35457012, 2022). "Suppression of Mcl-1 by norcantharidin induces mitochondrial-dependent apoptosis in human prostate cancer cells." (PMID 35457012, 2022). "of prostate cancer metastases showed that prostate cancer bone metastases had increased expression of MCL-1 (myeloid leukemia 1) and BCL-2 (B-cell lymphoma 2), key contributors in cell survival, compared to other sites of metastases." (PMID 36466910, 2022). "As with other solid malignancies, BCL-XL and MCL-1 appear to be more important than BCL-2 for cell survival in prostate cancer, although it is likely there is significant inter- and intra-patient heterogeneity." (PMID 35008216, 2021). "MDA-7/IL-24 also acted synergistically in colorectal cancer and prostate cancer cells when combined with the Apogossypol derivatives, BI-97C1 and BI-97D6, which are pharmacological inhibitors of Mcl-1." (PMID 35008495, 2021). "The agents that induce ER stress or inhibit protein synthesis decreased MCL1 expression and sensitized prostate cancer cells to apoptosis." (PMID 33668112, 2021). "At the same time, a more nuanced role of BIM in apoptosis was proposed, when increased BIM expression had an anti-apoptotic effect that was reversed by phosphorylation that prompted interaction with BCLX and MCL1 in prostate cancer cells." (PMID 33668112, 2021). "In contrast to the regulation of HIF-1α on PDGF, it has also been demonstrated that PDGF-BB treatment can rapidly increase the nucleus level of HIF-1 to activate transcription of myeloid cell leukemia-1 (Mcl-1) in human prostate cancer cells." (PMID 34445528, 2021). "MCL1 mRNA expression analysis suggests that it is the dominant anti-apoptotic protein of the BCL-2 family in prostate cancer cells." (PMID 33668112, 2021). "MCL-1 has also been implicated in resistance to ADT, and is upregulated in androgen deprived prostate cancer cells, preventing the induction of apoptosis." (PMID 35008216, 2021). "Activation of ADRB2/PKA signaling protected prostate cancer cells from apoptosis by increasing MCL1 expression via a transcription-independent mechanism." (PMID 33668112, 2021). "MCL-1 has also been shown to protect prostate cancer cells from chemotherapy-induced DNA damage and cell death." (PMID 35008216, 2021). "Sorafenib sensitizes prostate cancer cells to (-)-gossypol through the attenuation of Mcl-1 expression in vitro and in vivo." (PMID 32872659, 2020). "We found that CUDC‐907 induces apoptosis in prostate cancer cells and that this is at least partially mediated by Mcl‐1, Bcl‐xL, Bim and c‐Myc." (PMID 32459381, 2020). "It has been shown that ADRB2/PKA signaling can phosphorylate BAD and dissociate it from BCL-XL and also upregulate MCL-1 levels in prostate cancer cells." (PMID 30871232, 2019). "We previously demonstrated that exogenous expression of miR-29b inhibited anti apoptotic molecule Mcl-1 and metastasis in prostate cancer." (PMID 31752117, 2019). "Cancer genomic analysis using 13 multidimensional prostate cancer data sets showed that significantly higher genetic alterations were observed for AR (19%) and MCL1 (5%) genes among the CGS." (PMID 31816863, 2019).
prostate carcinoma (continued). "Previous studies have found that miR-29b can directly downregulate the translation of Mcl-1; this results in the inhibition of prostate cancer cells and tumor progression in an extrahepatic bile duct cancer cell line." (PMID 29662889, 2018). "Previous studies found that miR-29b can directly downregulate the translation of Mcl-1, thus inhibiting prostate cancer cells and extrahepatic bile duct cancer cell line tumor progression." (PMID 29662889, 2018). "Recently, miR-512-5p has been shown to modulate the expression of the apoptosis regulator MCL-1, and miR-296-5p has been demonstrated to reduce cell proliferation of breast and prostate cancer cells by targeting SCRIB or HMGA1, respectively." (PMID 29221158, 2017). "Sabutoclax is designed to specifically inhibit the BH3 binding domain of MCL-1 and has an MCL-1-selective activity in prostate cancer cells." (PMID 27846237, 2016). "CamKII is actually known to activate AKT/mTOR pathway and was demonstrated to down-regulate Mcl-1 in prostate cancer cells." (PMID 25627260, 2015). "Usp9X remains an interesting target as its levels are increased in glioblastoma and this molecule maintains high levels of certain anti-apoptotic factors, such as Mcl-1, Inhibitor of Apoptosis Proteins and a gene fusion observed in 40% of prostatic carcinomas." (PMID 26474387, 2015). "Mithramycin has been found to induce apoptosis by regulating the mTOR/Mcl-1/tsBid pathway in androgen-independent prostate cancer cells." (PMID 26484141, 2015). "According to previous studies, Mcl-1 is a crucial regulator of apoptosis and differentiation and is overexpressed in the majority of prostate cancer cells." (PMID 26252009, 2015). "MCL1 is proposed as a key target for Mithramycin A-induced apoptosis in androgen-independent prostate cancer cells and a tumor xenograft animal model." (PMID 26484141, 2015). "The expression of Bcl-2 family proteins (anti-apoptotic proteins including Bcl-2, Bcl-xL, and Mcl-1 and pro-apoptotic proteins including Bax and Bak) was then examined in the three prostate cancer cell lines." (PMID 25333266, 2014). "Here we report that a combination of MCL-1 loss and BAD dephosphorylation is sufficient to induce rapid apoptosis in PTEN-deficient advanced prostate cancer cells." (PMID 24040284, 2013). "Earlier, MCL-1 was implicated in anti-apoptotic signaling by IL-6 in LNCaP and Du145 prostate cancer cells, whereas downregulation of MCL-1 lead to apoptosis in two days." (PMID 24040284, 2013). "Activation of c-Abl by platelet derived growth factor (PDGF) promoted prostate cancer cell survival by inducing expression of the antiapoptotic protein, MCL-1, via a p68/β-catenin signaling pathway." (PMID 24223753, 2013). "The combination of MCL-1 knockdown and expression of phosphorylation-deficient mutant BAD2SA is sufficient to trigger rapid apoptosis in prostate cancer cells." (PMID 24040284, 2013). "We recently correlated overexpression of myeloid cell leukemia-1 (Mcl-1), a member of the Bcl-2 family, with the progression of prostate cancer (PCa) towards bone metastasis." (PMID 22276222, 2012). "Additionally, indirect downregulation of Mcl-1 was shown to sensitize prostate cancer cells to navitoclax." (PMID 40704654, 2025). "Unequal knockdown efficiencies in the two prostate cancer cell lines might result from varying Mcl-1 stabilities." (PMID 37173959, 2023). "Because Mcl-1 is the most overexpressed anti-apoptotic gene in senescent cancer cells, including Bcl-2-negative senescent tumor cells, pharmacologically suppressing Mcl-1 can ultimately eradicate senescent prostate cancer cells, preventing the spread of the tumor and metastases." (PMID 36980256, 2023). "Mcl-1 and USP9x immunoreactivity increased with prostate cancer progression." (PMID 37173959, 2023). "We further analyzed whether and how radiotherapy, which is commonly applied to patients with progressed prostate cancer, affected Mcl-1 protein levels and its turnover in LNCaP and PC3 cells." (PMID 37173959, 2023).